PAK4 (p21 (RAC1) activated kinase 4)
Diseases named in the same sentence as PAK4 in open-access papers (continued):
Sharing a sentence is not in itself a finding about the gene and the disease.
tumor (continued). "PAK4 knockout increased vessel diameter, enhancing gemcitabine sensitivity, but failed to regress tumour growth." (PMID 41228228, 2025). "However, to directly examine the activation of CD8+ T cells by PAK4 KO tumor cells, a co-culture study of human CD8+ T cells with PAK4 KO human PDA cells will be required." (PMID 39941877, 2025). "Conversely, PAK4 and UCHL1 showed elevated levels in NATs compared to tumor samples." (PMID 39199615, 2024). "To investigate whether PAK4 inhibition could affect the distribution of immune cells in vivo, we examined alterations in the proportion of different immune cells in OSCC tumour-bearing mice following the administration of the PAK4 inhibitor." (PMID 38890401, 2024). "Pak4 expression showed positive correlation with tumor purity (cor = 0.128, p = 4.95e-03), negative correlation with B cell infiltration (partial." (PMID 38807162, 2024). "Tumour purity adjusted estimation of intra-tumoral B and T cell infiltration showed a negative correlation between PAK4 and CD8 + T cell infiltration, but not with B cells or CD4 + T cells." (PMID 38797819, 2024). "The proportion of CD8+ T-cells was significantly increased in the tumours, but not in the peripheral blood, cervical lymph nodes, peripheral lymph nodes, and spleen of PAK4 inhibitor-treated mice compared with that in the respective tissue of control mice." (PMID 38890401, 2024). "Given that both PAK1 and PAK4 play important roles in PDA biology, we hypothesize that the two may promote PDA tumour growth synergistically." (PMID 38797819, 2024). "In addition, the PAK4 inhibitor increased the expression of MHC and immune co-stimulatory molecules in tumour-infiltrated CD103+ DCs." (PMID 38890401, 2024). "Notably, genetic and pharmacological ablation of PAK4 in ECs reshapes the immune landscape within the TME, improving T-cell infiltration and sensitizing tumor to CAR-T cell therapy." (PMID 38580870, 2024). "We report that PAK4 inhibition reverses immune cell exclusion by increasing the infiltration of CD8 T cells and CD103+ dendritic cells (DC), a specific type of DCs that excel at cross-presenting tumor antigens and constitute a source of CXCL10." (PMID 36588582, 2022). "PAK4 KO anti-PD-1 treated tumors also showed a high level of spatial colocalization of these two markers, suggesting a proper functionality of these blood vessels and an active migration of CD8+ cells into the tumor." (PMID 36588582, 2022). "In addition, due to the lack of PAK7 data in the GSVA database, we grouped 28 tumor patients according to the methylation status of PAK1, PAK2, PAK3, PAK4, and PAK6, respectively, and then analyzed the survival difference of tumor patients." (PMID 36064705, 2022). "Here, we show how PAK4 inhibition increases not only T-cell infiltration, but also CD103+ dendritic cell (DC) infiltration, an important subset of dendritic cells that excel at cross-presenting tumor antigens and priming T cells." (PMID 36588582, 2022). "Ribas and co-workers recently conducted a transcriptional analysis of tumor biopsies, and found that PAK4 expression is enriched in immune cell poorly infiltrated non responding tumors." (PMID 36105226, 2022). "In colorectal cancer (CRC), high PAK4 expression is closely related to serous layer infiltration and advanced tumor stage but has no connection with lymph node metastasis and disease-free survival (DFS)." (PMID 35800076, 2022). "Pfizer compound PF-3758309, initially designed to be a PAK4-specific ATP-competitive inhibitor, disrupted PAK4-dependent cell adhesion and anchorage-independent growth in MDA-MB-231 xenograft tumour models, corresponding to an 89% reduction in BCa tumour growth." (PMID 35385780, 2022). "Since previous studies have revealed that PAK4 is involved in tumor cell infiltration by immune cells through regulation of WNT/β-catenin pathway, PAK4-targeted inhibitors may have synergic effect with PD-1/PD-L1 checkpoint blockades." (PMID 36105226, 2022).
tumor (continued). "A recent study suggests that PAK4 is enriched in nonresponding tumor biopsies, and we also observed that PAK4 was significantly more highly expressed in the immune‐suppressed subtype than in the immune‐activated subtype (P = 0.037)." (PMID 33338321, 2021). "We conclude that LINC01088 might function as a tumor suppressor, inhibiting the tumorigenesis of ovarian epithelial cells through LINC01088/ miR-24-1-5p/ PAK4 axis." (PMID 29440672, 2018). "In summary, high PAK4 expression is correlated with non-responding tumor biopsies with low T and dendritic cell infiltration, and inhibition of PAK4 overcomes resistance to PD-1 blockade in a CD8 dependent manner." (PMID 30400822, 2018). "PAK4 is a member of the PAK family, which is closely related to human tumor." (PMID 27297086, 2016). "Furthermore, we found that PAK4 bound to LIM kinase 1 (LIMK1) directly and activated it via phosphorylation, which is required for tumor cell motility and invasion." (PMID 25975262, 2015). "Furthermore, we confirmed the significant CD8+T-cell stimulatory function of tumour-infiltrated CD103+ DCs in PAK4 inhibitor-treated mice compared with that in non-treated mice via an in vitro T-cell proliferation assay." (PMID 38890401, 2024). "Moreover, PAK4 expression was immunohistochemically detected in tissue samples from patients with OSCC in the tumour area, but not in the adjacent normal area." (PMID 38890401, 2024). "Therefore, the tumour was completely regressed by PAK1 and PAK4 double knockout." (PMID 38797819, 2024). "Furthermore, the blood vessel density stained by PECAM1 (CD31) showed a trend of elevation in the PAK4 knockdown (KD) tumour, despite not reaching statistical significance." (PMID 38067120, 2023). "The multi-omics analysis of bioinformatics revealed that PAK4 is rich in the “T cell receptor signaling pathway” regulates macrophage polarization through heat shock protein 105 kDa (HSPH1), and significantly impacts neoantigen production and tumor immune regulation." (PMID 35800076, 2022). "PAK4-negative PC exhibits larger tumor volume and poor histological differentiation." (PMID 35800076, 2022). "Due to the strong nature of the PyMT oncogene, it is likely that cells where only PyMT is expressed may eventually contribute to subpopulations of tumor cells, where PAK4 is not subjected to Cre-mediated knockout." (PMID 31399573, 2019). "To investigate the implication of PAK4 and NAMPT in PNET therapy resistance and survival, we first evaluated the basal expression level of these two proteins in PNET cell lines (BON-1 and QGP-1) and patient-derived tumor tissue using Western blotting and RT-qPCR." (PMID 31795447, 2019). "The behavior of such cells is likely not affected by Cre-mediated PAK4 depletion and hence, these cells may contribute as well to the tumor masses." (PMID 31399573, 2019). "Furthermore, tumor biopsies from patients without a response to PD-1 blockade showed increased levels of PAK4 expression (p-value = 0.004)." (PMID 30400822, 2018). "Furthermore, it remains to be investigated whether the role of PAK4 in CDDP resistance development is non-specific to certain tumour cells." (PMID 27919028, 2014). "The double knockout of PAK1 and PAK4 did not inhibit tumour growth, although it stimulated vascular normalisation, indicating an outcome balanced between PAK1 and PAK4." (PMID 41228228, 2025). "The double knockout of PAK1 and PAK4 did not inhibit tumour growth significantly, but stimulated vascular normalisation, indicating an outcome balanced between PAK1 and PAK4." (PMID 41228228, 2025). "PAK1&4KO didn’t reduce angiogenesis nor tumour growth, but promoted vascular normalisation, indicating the outcomes after balancing of PAK1 and PAK4." (PMID 41228228, 2025). "Consistent with animal studies, immunoblotting analysis of liver tissues obtained from HCC patients indicated higher levels of PAK4, total-, phospho-, and nuclear-NCoR1, and lower levels of HMGCS2 in tumor compared to non-tumorous tissues." (PMID 37591884, 2023).
tumor (continued). "PAK4 can be activated by cAMP–PKA to enhance CREB transcription activity independent of phosphorylation at Ser133 residue, and PAK4 knockdown in PC-3 and DU145 cells inhibit tumor formation in nude mice." (PMID 33292604, 2020). "Moreover, the expression of β-catenin in tumour cells of the OSCC tumour-bearing mice, with or without PAK4 inhibitor treatment, was also compared." (PMID 38890401, 2024). "However, by four weeks, the kinase activities of IKKε and PKCθ were no longer different between PAK4 KO and WT tumours suggesting an immune evasion of PAK4KO tumour after the initial response." (PMID 38797819, 2024). "We observed that PAK4 KO tumors, regardless of anti-PD-1 treatment, significantly increased the percentage of CD103+ DC, a subset of dendritic cells that have been described to excel at cross-presenting tumor antigens." (PMID 36588582, 2022). "The fact that PAK4 KO cells do not secrete any CCL21 suggests that, although another cell type is responsible for the secretion of this chemokine, the absence of PAK4 might contribute to increase its concentration in the tumor microenvironment." (PMID 36588582, 2022).
infection (5 papers, 2015 to 2024). The state of being infected such as from the introduction of a foreign agent such as serum, vaccine, antigenic substance or organism. "Subsequently, cells were harvested at 6 and 12 h post infection and the expression and phosphorylation of PAK4 were detected by using Western-blot." (PMID 28680855, 2017). "For example, PAK4 is in the reconstructed network showing its effect after infection at time points 10 and 20 min." (PMID 26257716, 2015). "Given that productive infection of JEV is required to stimulate PAK4 activation, we speculated that replication of viral genomic RNA may play a key role." (PMID 28680855, 2017). "Flow cytometry results show that siRNA silencing the expression of SGK3, ULK3, ERBB4, STK17B can reduce the infection efficiency of ORFV-GFP virus, while siRNA silencing the expression of MST1R, PAK4, ERBB3 can increase the infection of ORFV-GFP virus efficient." (PMID 35401439, 2022). "The phosophorylation and expression level of PAK4 were shown to have no significant changes, indicating that productive infection of JEV is essential requirement for PAK4 activation." (PMID 28680855, 2017). "In our experiments, we found out the infection and replication abilities of ORFV were not affected after the expression of PAK4 was silenced by using siRNA." (PMID 35401439, 2022).
metabolic disease (2 papers, 2023 to 2026). A congenital disorder (due to inherited enzyme abnormality) or acquired (due to failure of a metabolically important organ) disorder resulting from an abnormal metabolic process. "PAK4 in fetal hepatocytes was implicated in the sexual dimorphism of metabolic disease through the regulation of de novo lipogenesis." (PMID 36672500, 2023). "Accumulating evidence indicates that aberrant overexpression of PAK4 contributes to the progression of metabolic diseases, whereas reduced PAK4 activity may provide protective benefits." (PMID 41735496, 2026). "Here we highlight recent advances in understanding the regulatory role of p21-activated kinase 4 (PAK4), the prototypical group II PAK family member, in metabolic diseases." (PMID 41735496, 2026).
of the pancreas (1 paper, 2017). "Given that complete PAK4 gene depletion in the mouse causes embryonic lethality, our model for conditional PAK4 gene depletion in the mouse pancreas will become a useful tool to examine the role of PAK4 in diseases of the pancreas." (PMID 28765528, 2017).
PAK4 also shares sentences with these, for which no sentence is quoted: lung adenocarcinoma (4 papers); adenomyosis (2); bladder cancer (2); breast invasive carcinoma (2); cholangiocarcinoma (2); choriocarcinoma (2); cognitive deficits (2); follicular lymphoma (2); Lung Injury (2); mantle cell lymphoma (2); myocardial infarct (2); pancreatic ductal adenocarcinoma (2); prostate tumor (2); type 2 diabetes (2); adenocarcinoma (1); age (1); amyotrophic lateral sclerosis (1); bladder urothelial carcinoma (1); cardiovascular disease (1); cerebral infarction (1); gastric tumours (1); HIV-1 infection (1); intestinal tumour (1); ischemic stroke (1); kidney cancer (1); laryngeal carcinoma (1); liver disease (1); mammary adenocarcinoma (1); metastatic cancer (1); MODY (1).
A further 8 diseases each share a sentence with PAK4 in 1 paper.